COL1A1 (collagen type I alpha 1 chain)
Diseases named in the same sentence as COL1A1 in open-access papers (continued):
Sharing a sentence is not in itself a finding about the gene and the disease.
pulmonary fibrosis (continued). "Similarly to cardiac fibrosis, circHIPK3 increases the expression levels of SOX4 and COL1A1 by binding miRNA-338-3p in pulmonary fibrosis and thus promoting the progress of pulmonary fibrosis." (PMID 33693013, 2021). "In contrast, upregulating the expression of miR-497-5p could induce the expression of Acta2 and Col1a1 and contribute to the phenotype of pulmonary fibrosis by activating the Mmps/TGF-β pathway." (PMID 28098218, 2017). "We went on to determine whether miR-29b Psh-match can suppress the expression of the fibrosis-related gene Col1a1 in pulmonary fibrosis model mice." (PMID 28234907, 2017). "From our findings, IL-6 from cancer cells could induce COL1A1 and α-actin expression in lung fibroblast cells, suggesting IL-6 was likely one of the important factors for lung fibrosis." (PMID 23592411, 2013). "Interestingly, only COL1A1 was also upregulated at the early stages of pulmonary fibrosis." (PMID 39388499, 2024). "These pFBs are crucial for the development of pulmonary fibrosis, as indicated by robust increases in collagen triple helix repeat containing 1 (CTHRC1) that regulates collagen matrix deposition, and the pathogenic ECM components such as collagen type I alpha 1 chain (COL1A1) and COL3A1." (PMID 38846354, 2024). "Therefore, the expression of ENST00000313807 and COL1A1 in plasma cirexos may become an important indicator for the evaluation of pulmonary fibrosis, as well as a biomarker for the diagnosis of SSc-ILD." (PMID 36873898, 2023). "Similarly, the increase in COL1A1 mRNA levels in the presence of TGFβ was attenuated by miR-338-3p in a human lung fibroblast cell line, a human embryonic kidney cell line as well as in vivo in a bleomycin induced mouse model of pulmonary fibrosis." (PMID 37373151, 2023). "miR-33M/M–/– mice were protected from bleomycin-induced lung fibrosis, as indicated by a reduction in collagen content, measured by hydroxyproline assay (fold change, –2; P ≤ 0.0001) and expression of profibrotic genes including Col1a1 and Acta2 (fold change, –2.5; P ≤ 0.0001)." (PMID 36626225, 2023). "Fibrosis-related genes include Col1a1, Acta2, Fn1, and Tgfb1 gene, and senescence-related genes composed of Cdkn2a, Tnf, Serpine1, Ccl2, Mmp10, and Mmp12 gene, all of which reflected the intensity of lung fibrosis and senescence events in lung tissue and pulmonary fibroblasts." (PMID 35662697, 2022). "Similarly, MPs isolated from SSc patients with lung fibrosis showed a greater profibrotic profile, with an upward trend for Col1a1/MMP1 (median of 1.59 vs. 0.65, p=0.1) and Col1a2/MMP1 ratio (median of 2.42 vs. 0.91, p=0.07), but reduced ability to induce CCL2 (median of 0.89 vs. 1.51, p<0.05)." (PMID 33193304, 2020). "Fibronectin 1 (Fn1), a key ECM component in pulmonary fibrosis, was upregulated upon TGF-β1 stimulation, along with Acta2, Col1a1, and Col3." (PMID 40867551, 2025). "Pirfenidone, used as treatment for pulmonary fibrosis, proved to be effective preventing an increase in COL4A1 and COL1A1 during OCT culture." (PMID 40104066, 2025). "Results showed that mice treated with AAV9‐shSema3E exhibited lower protein and mRNA levels of Fibronectin, Col1a1, and α‐SMA expression following BLM‐induced pulmonary fibrosis compared to AAV9‐NC mice." (PMID 40112179, 2025). "The relative mRNA expressions of periostin, fibronectin, collagen type I alpha 1 (Col1a1), and alpha-smooth muscle actin (α-SMA) were significantly elevated in both WT and TG mice with lung fibrosis compared to their respective saline-treated controls." (PMID 39329706, 2024). "Meanwhile, we also examined the gene and protein expression of lung fibrosis-related molecules (TGF-β1, Fn1, and Col1a1)." (PMID 38474239, 2024). "The levels of TGF-β, COL1A1, and α-SMA and degree of pulmonary fibrosis at 10 weeks after radiation were also decreased by Syk inhibitor." (PMID 39575431, 2024).
pulmonary fibrosis (continued). "Further detection results of pulmonary fibrosis-related markers showed that PDGF-BB induction increased the expression levels of major ECM components, including COL1A1, COL3A1, LN, FN, and α-SMA." (PMID 37138491, 2024). "For further assessment of the nintedanib effects on the fibrotic response, the expression levels of biomarkers (α-SMA, COL1A1 and CTGF) involved in pulmonary fibrosis development were analyzed through IHC staining." (PMID 38993568, 2024). "Overexpression of miR-27b in lung fibrosis mice and LL29 cells was found to suppress the expression of COL1A1, COL3A1, COL4A1, and α-SMA induced by TGF-β1, thereby reducing cellular contractility." (PMID 39479511, 2024). "MiR-26a functions as an endogenous inhibitor of the TGF-β1/Smad signaling pathway, and its downregulation in IPF and pulmonary fibrosis mice models leads to the upregulation of CTGF, COL1A1, and COL3A1." (PMID 39479511, 2024). "At the in-vivo condition, our findings demonstrated that ISO treatment effectively induces cardiac (and pulmonary) fibrosis, characterized by pro-fibrotic and pro-inflammatory gene expression and IHC (α-SMA, COL1A1, and TGFβ)." (PMID 39388499, 2024). "Lung fibrosis is characterized by the deposition of ECM proteins, including COL1A1, combined with collagen I as the most abundant ECM component in both normal and fibrotic conditions." (PMID 37794454, 2023). "There was an increase in microcomputed tomography (CT), Ashcroft score, and mRNA levels of fibrotic markers COL1A1 and FSP‐1 in mice after BLM challenge over time, indicating the success of BLM‐induced pulmonary fibrosis." (PMID 37693057, 2023). "Collagen I has a triple helix structure that arises from two α-1 and one α-2 chains, which are the products of the COL1A1 and COL1A2 genes, respectively; down-regulation of COL1A1 alleviates the accumulation of ECM and then inhibits pulmonary fibrosis." (PMID 37794454, 2023). "Myofibroblasts are rich in intracellular proteins, such as Vimentin and α-smooth muscle actin (α-SMA), while producing ECM proteins, such as Collagen Type I Alpha 1 (COL1A1), which are the hallmarks of pulmonary fibrosis." (PMID 36677811, 2023). "We identified three genes of interest (SPP1, COL1A1, and VEGFA) by bioinformatics analysis that were verified by qPCR in samples of TGF-β1-induced HFL fibroblast cells and pulmonary fibrosis mice." (PMID 37794454, 2023). "In contrast, we find an enrichment of several markers of pulmonary fibrosis (CLU, COL1A1, COL1A2, and COL3A1) in SARS-CoV-2-low patients (these correspond to the later stages of infection), indicating that there are two distinct stages of infection." (PMID 35233546, 2022). "Col1a1, Col1a2, and α-SMA are considered the main pulmonary fibrosis markers, and their levels reflect the degree of pulmonary fibrosis." (PMID 36182915, 2022). "Our results showed that, compared with the silica group, the silica + KC7F2 group showed reduced expression of HIF-1α, COL1A1, α-SMA, and PSMAD3 and reduced lung fibrosis." (PMID 35682354, 2022). "HuR appears to function via direct binding to mRNAs for COL1A1, COL3A1, ACTA2, and FN, and it was found that HuR is localized to a greater degree in the cytosol in cells from mouse lung fibrosis models as well as human idiopathic pulmonary fibrosis patients." (PMID 35892569, 2022). "To further assess the effects of DHM on pulmonary fibrosis, we detected the levels of fibrotic markers (α-SMA, Col1a1, and fibronectin) by western blot analysis." (PMID 35359847, 2022). "In the lung of BLM-induced pulmonary fibrosis mice, SOX4 and COL1A1 expression was significantly upregulated." (PMID 30796204, 2019). "In BLM-induced pulmonary fibrosis mice, circHIPK3 silencing significantly decreased SOX4 and COL1A1 expression." (PMID 30796204, 2019).
pulmonary fibrosis (continued). "In order to assess the therapeutic effects of PFD, fibrosis-related factors IL-6 and COL1A1 levels in MLF supernatant induced by TGF-β1, as well as those in serum and BALF of mice with BLM-induced pulmonary fibrosis were estimated." (PMID 28420366, 2017). "CCL2 promotes the expression of COL1A1 protein and α-SMA proteins, suggesting that the mechanism of inflammation-induced pulmonary fibrosis may involve the regulation of COL1A1 and α-SMA by CCL2." (PMID 40606673, 2025). "Additionally, treatment with UGRP1 protein significantly promoted the pulmonary fibrosis of young mice, as shown by the increased Masson staining, Ashcroft score, tissue levels of HYP and expression levels of Col1a1, Timp1 and α-SMA." (PMID 36934284, 2023). "In this study, BLCN-induced pulmonary fibrosis was indicated after calculating the fibrosis score, immunohistochemical examination of the expression of ACTA2, the gene expression level of col1a1, hydroxyproline lung content, and the protein expression levels of TIMP-1 and PDGF-BB." (PMID 37631038, 2023). "BLM-induced pulmonary fibrosis was significantly prevented in CCL6-neutralized aged mice, as shown by the decreased Masson staining and Ashcroft score, reduced tissue levels of HYP, and reduced expression levels of Col1a1, Timp1, and α-SMA." (PMID 36934284, 2023). "ITGA8 deletion increased COL1A1 production during lung fibrosis in vitro, but did not affect pulmonary fibrosis in the bleomycin animal model." (PMID 33119648, 2020). "Consistent with the induction of lung fibrosis by BLM, the transcript expression levels of various fibrogenic protein genes including Col1a1, Col3a1, Eln, Fn, Ctgf, as well as Txndc5, were significantly upregulated in BLM-treated mouse lungs (21 days post-BLM treatment)." (PMID 32848143, 2020). "Notably, LAM MACs were similar to the fibroblasts identified in pulmonary fibrosis, which also express COL3A1, COL1A1, and ACTA233." (PMID 33159078, 2020). "Thus, both predicted direct targets CTGF and Col1a1 or un-predicted targets Col4a1 and α-SMA are down-regulated after miR-133a overexpression, strongly suggesting an anti-fibrotic role of miR-133a in pulmonary fibrosis." (PMID 31511493, 2019). "A specific knockout of the Col1a1 gene in fibrocytes, furthermore, yielded no significant impact on pulmonary fibrosis, even though up to 30% of collagen producing cells are assumed to be fibrocytes, suggesting a crucial role of paracrine functions." (PMID 31591328, 2019). "Pulmonary fibrosis began one week after BLM-injection and reached a maximum level after 3–4 weeks, as evaluated by Masson trichrome (MT) staining and type 1 collagen 1 (COL1A1) immunostaining." (PMID 29415439, 2018). "Also, BLM up-regulated COL1A1 and IL-6 levels in serum and BALF of mouse with pulmonary fibrosis, and level of COL1A1 in BLM 42d is higher than BLM 14d group." (PMID 28420366, 2017). "Here, our results demonstrated that the expressions of fibrosis-related cytokines IL-6 and myofibroblast markers COL1A1 were significantly increased in the supernatant of TGF-β1 induced MLF, serum, and BALF in mice with BLM-induced pulmonary fibrosis, especially in BLM 42d group." (PMID 28420366, 2017). "Using a bleomycin-induced pulmonary fibrosis mouse model, the team further observed that L005-B (doses ranging from 0 to 1,000 μg/mL for 48 h) administration significantly reduced fibrotic markers (α-SMA, COL1A1, and fibronectin) while restoring E-cadherin expression in vivo." (PMID 41368573, 2025). "In addition, CC-11050 treatment significantly downregulated the expression of genes that play a key role in lung fibrosis, such as TGFB1 (16 dpi; p=0.0433), COL1A1 (16 dpi, p=0.009), TAGLN (16 dpi; p=0.0218), MYH11 (4 dpi; p=0.0042; 16 dpi; p=0.05) and SMAD2 (16 dpi; p=0.008)." (PMID 37854602, 2023).
pulmonary fibrosis (continued). "However, QLJP inhibited the TGF-β1/Smad2 signaling pathway, down-regulated the expression levels of α-SMA, COL1A1, MMP2, and improved pulmonary fibrosis and pulmonary arteriole remodeling induced by low-temperature exposure to play a role in the prevention and treatment of PAH." (PMID 36611616, 2022). "The chronization of asthma and development of lung fibrosis was shown to either not affect observed asthma-driven upregulation of the genes, as in the case of Col1a1, Col4a1, and Col4a2, or downregulate the expression of Thbs2 and Tyrobp almost to the level of healthy control." (PMID 35625754, 2022). "Similarly, we find enrichment of several markers of pulmonary fibrosis (CLU, COL1A1, COL1A2, and COL3A1) in SARS-CoV-2-low samples as compared with nonviral and viral ARDS samples, exemplifying the profound lung injury and fibrosis during later stages of COVID-19." (PMID 35233546, 2022). "Additionally, bleomycin-insulted mice showed increased lung levels of TGF-β1 and total collagen concentration, as measured by ELISA, and increased lung expression of COL1A1 and α-SMA, as assessed by Sircol Collagen Assay kit or Western blot analysis; all these are indices of pulmonary fibrosis." (PMID 28408888, 2017). "Though IPF lung fibroblasts responded to heparin + FGF1 treatment by attenuating COL1a1 expression and increased apoptosis, increased p-ERK1/2 signaling along with enhanced cell migration was also observed reflecting a potentially dual nature of FGF1/FGFR in the context of lung fibrosis." (PMID 26138239, 2015).
breast carcinoma (110 papers, 2005 to 2025). "For example, in breast cancer, high expression of COL1A1 has been associated with worse OS and distant metastasis." (PMID 38913913, 2024). "For instance, in breast cancer, up-regulated COL1A1 has been associated with tumor growth, invasion, and metastasis, promoting a pro-tumorigenic microenvironment." (PMID 38913913, 2024). "In this study, the role and mechanism of COL1A1 in inducing fibroblasts to transform into tumor-associated fibroblasts and promoting matrix remodeling of breast cancer was investigated." (PMID 38045487, 2023). "Recently, Col1A1 mRNA expression was reported to be associated with bone metastases in ccRCC and breast cancer." (PMID 34539753, 2021). "For example, in breast cancer, the increased COL1A1 level was associated with poor survival, especially in patients with ER + breast cancer." (PMID 34399848, 2021). "COL1A1, a major component of collagen type I, is upregulated and is associated with tumor metastasis in various cancers, such as breast cancer, hepatocellular carcinoma, gastric cancer, CRC, non-small-cell lung cancer, prostate cancer, and cervical cancer." (PMID 32612946, 2020). "Further, high expression of the COL1A1 gene and protein has been associated with shorter recurrence free and overall survival in breast cancer, as well as with response to cisplatin." (PMID 31488082, 2019). "Type III collagens (COL3A1) are associated with more benign, non-invasive breast cancers, and expression of type I collagens (COL1A1) are associated with invasive phenotypes." (PMID 29854878, 2018). "Using gene co-expression analysis, we showed that P4HA2 was associated with expression of Col1A1, Col3A1, and Col4A1 during breast cancer development and progression." (PMID 24383403, 2014). "Except for COL1A1-rs2075555, we successfully replicated the association of ten consortia reported breast cancer susceptibility loci in our study population at P<0.05." (PMID 23717390, 2013). "Studies have shown that COL1A1 overexpression is strongly linked to malignant phenotypes, increased invasiveness, and poor prognosis in several cancers, including gastric cancer, breast cancer, pancreatic ductal adenocarcinoma, and lung cancer." (PMID 40851082, 2025). "However, the role of COL1A1 in tumor-associated fibroblast activation and matrix remodeling in the tumor microenvironment of breast cancer remains largely known." (PMID 38045487, 2023). "Of the other identified proteins associated with breast cancer, COL1A1 and COL1A2, the two components of type I collagen, were shown to be upregulated in invasive breast cancer, with a potential role in spinal metastasis, although not proposed as potential targets." (PMID 31139569, 2019). "Upregulation of NNMT maintains the cancer-associated fibroblast phenotype, activates the PRDM5/COL1A1 axis, and promotes tumor metastasis in gastric cancer and breast cancer (BC)." (PMID 39399490, 2024). "While the direct interplay between COL1A1 and CTCs remains unexplored in PCa, previous studies in breast cancer models have shown that COL1A1-accumulating mice have larger lung metastases and more CTCs46." (PMID 40093812, 2025). "And it can promote breast cancer progression by regulating the expression of Collagen Type I Alpha 1 Chain (COL1A1)." (PMID 40909283, 2025). "Studies in breast cancer have reported that COL1A1 supports cell migration and invasion through various signaling pathways." (PMID 38963646, 2025). "In this study, we found that COL1A1 was a poor predictor for long-term survival of breast cancer brain metastasis, and oncology analyses showed that focal adhesion was a major biological process in which COL1A1 participated." (PMID 39157383, 2024). "The overexpression of COL11A1 and COL1A1 plays a crucial role in the metastasis of gastric, breast, and colorectal cancers, as well as in the development of tamoxifen resistance in breast cancers." (PMID 39682235, 2024).